RN7SL391P (RNA, 7SL, cytoplasmic 391, pseudogene)
Gene: Miscellaneous RNA gene on chromosome 12 (6,344,554 to 6,344,837, forward strand). Ensembl gene ENSG00000265388.
Homologues: Orthologues: chimpanzee Metazoa_SRP (82% identical), macaque Metazoa_SRP (80% identical), macaque Metazoa_SRP (75% identical). Paralogues in human: Metazoa_SRP (84% identical), RN7SL96P (84% identical), RN7SL774P (83% identical), Metazoa_SRP (82% identical), RN7SL474P (82% identical), RN7SL488P (81% identical), Metazoa_SRP (81% identical), RN7SL134P (81% identical), RN7SL811P (81% identical), RN7SL693P (81% identical), RN7SL163P (80% identical), RN7SL784P (80% identical), and 712 more.